AP4S1 (adaptor related protein complex 4 subunit sigma 1)
Description:
Component of the adaptor protein complex 4 (AP-4). Adaptor protein complexes are vesicle coat components involved both in vesicle formation and cargo selection. They control the vesicular transport of proteins in different trafficking pathways. AP-4 forms a non clathrin-associated coat on vesicles departing the trans-Golgi network (TGN) and may be involved in the targeting of proteins from the trans-Golgi network (TGN) to the endosomal-lysosomal system. It is also involved in protein sorting to the basolateral membrane in epithelial cells and the proper asymmetric localization of somatodendritic proteins in neurons. AP-4 is involved in the recognition and binding of tyrosine-based sorting signals found in the cytoplasmic part of cargos, but may also recognize other types of sorting signal (Probable).
Synonyms: CLA20; AP47B; SPG52; CLAPS4; CPSQ6
Tractability: Antibody: UniProt places it where antibodies can reach, with high confidence. PROTAC: ubiquitination databases record sites on it; its protein half-life has been measured.
Gene: Protein-coding gene on chromosome 14 (31,024,996 to 31,130,996, forward strand). Ensembl gene ENSG00000100478.
Subcellular location: Golgi apparatus, trans-Golgi network membrane
Subcellular location (Human Protein Atlas): Vesicles
Pathways (Reactome):
Vesicle-mediated transport: Lysosome Vesicle Biogenesis
Gene Ontology:
Biological process: intracellular protein localization; protein targeting; vesicle-mediated transport; protein transport
Cellular component: AP-4 adaptor complex; endosome lumen; trans-Golgi network; trans-Golgi network membrane; cytoplasm; endomembrane system; Golgi apparatus
Genetic constraint (gnomAD): Loss-of-function variants: 22 observed, 18.59 expected, observed/expected ratio (o/e) 1.18, 90% interval 0.84 to 1.67. The upper end of that interval is the gene's LOEUF score, 1.67, which puts it in group 6 of 6, group 1 being the genes least tolerant of losing a copy. Missense variants: 144 observed, 149.67 expected, observed/expected ratio (o/e) 0.96, 90% interval 0.84 to 1.11. Synonymous variants: 39 observed, 47.93 expected, observed/expected ratio (o/e) 0.81, 90% interval 0.63 to 1.06.
Gene-disease validity (ClinGen):
ClinGen rates the evidence that AP4S1 causes each of these diseases.
AP-4 deficiency syndrome (autosomal recessive): Definitive. A genetic disorder associated with variation(s) in the AP4 genes: AP4B1, AP4E1, AP4M1, and AP4S1.
Homologues: Orthologues: rabbit AP4S1 (99% identical), dog AP4S1 (98% identical), rat Ap4s1 (97% identical), guinea pig AP4S1 (96% identical), mouse Ap4s1 (96% identical), zebrafish ap4s1 (78% identical), chimpanzee AP4S1 (76% identical), macaque AP4S1 (76% identical), pig AP4S1 (72% identical), tropical clawed frog ap4s1 (56% identical). Paralogues in human: AP2S1 (42% identical), AP3S1 (40% identical), AP1S2 (38% identical), AP3S2 (37% identical), AP1S3 (35% identical), AP1S1 (35% identical).
Diseases named in the same sentence as AP4S1 in open-access papers:
AP4S1 is named in the same sentence as 16 diseases in open-access papers, as found by Europe PMC text mining. Sharing a sentence is not in itself a finding about the gene and the disease. The quoted sentences say what the papers report.
hereditary spastic paraplegia (4 papers, 2020 to 2025). Hereditary spastic paraplegias (HSP) comprise a genetically and clinically heterogeneous group of neurodegenerative disorders characterized by progressive spasticity and hyperreflexia of the lower limbs. "In this study, we report a rare homozygous variant (NM_001128126.3:c.295-3C>A) in the AP4S1 gene in two patients, who are siblings of Rwandan descent, with hereditary spastic paraplegia (SPG)." (PMID 40428364, 2025). "Indeed, mutations in genes encoding all subunits of AP-4 (ε1; AP4E1, β1; AP4B1, μ1; AP4M1 and σ1; AP4S1) have been identified as leading to a complex form of hereditary spastic paraplegia (HSP) termed AP-4 deficiency syndrome (henceforth AP-4 deficiency)." (PMID 31142229, 2020).
Intellectual disability (3 papers, 2013 to 2025). "The clinical features observed in our two Rwandan siblings, including early-onset spasticity, motor developmental delay, intellectual disability, and seizures, are consistent with previous reports of SPG52 caused by AP4S1 mutations." (PMID 40428364, 2025). "For instance, most subtypes of CP that involve mental retardation are induced by recessive variations in the genes of 4 protein-binding complexes (AP4M1, AP4E1, AP4S1, and AP4B1)." (PMID 36323241, 2023).
Spastic paraplegia (2 papers, 2013 to 2025). Complete loss of the ability to move the lower limbs accompanied by spasticity of the lower limbs. "Therefore, the presence of homozygous pathogenic mutations in the AP4S1 gene has confirmed the diagnosis of spastic paraplegia, aligning with the patient’s clinical presentation." (PMID 40428364, 2025).
developmental delay (1 paper, 2025). "Studies indicated that homozygous pathogenic mutations in the AP4S1 gene are associated with neonatal hypotonia that progresses to hypertonia and spasticity in early childhood, developmental delay, mental retardation, and poor or absent speech." (PMID 40428364, 2025). "Of specific interest, the identical AP4S1 variant (c.295-3C>A) was described in two African sisters with SPG52, who manifested with progressive spastic paraplegia, profound developmental delay, and foot deformities, but with an earlier age of onset (4–5 years) than our patients (3–5 years)." (PMID 40428364, 2025). "The observed phenotype included early-onset progressive lower limb spasticity, developmental delay, hyper-reflexia, and gait abnormalities, clinical features that are consistent with autosomal recessive hereditary spastic paraplegia type 52 (SPG52), previously associated with AP4S1 variants." (PMID 40428364, 2025).
hereditary spastic paraplegia type 52 (1 paper, 2025). "Hereditary spastic paraplegia type 52 (SPG52) is an autosomal recessive neurodevelopmental disorder caused by mutations in the AP4S1 gene, which encodes a subunit of the adaptor protein complex 4 (AP-4)." (PMID 40428364, 2025). "This case report adds to the growing body of literature by documenting a rare AP4S1 variant in non-consanguineous siblings of Rwandan descent with hereditary spastic paraplegia type 52." (PMID 40428364, 2025).
lysosomal disorders (1 paper, 2022). "In fact, isolated cases with GP hypointensities consistent with iron excess are known in at least 17 distinct genes, including AP4M1 and AP4S1, which, like FUCA1, GLB1, and TPP1, are involved in lysosomal disorders." (PMID 36233161, 2022).
polymicrogyria (1 paper, 2023). A developmental brain abnormality characterized by an excessive amount of small convolutions on the surface of the brain and cognitive dysfunction.
Spastic tetraplegia (1 paper, 2025). Spastic paralysis affecting all four limbs. "Disruptions in any of the complex’s subunits, including AP4S1, are associated with similar autosomal recessive phenotypes primarily characterized by spastic tetraplegia." (PMID 40428364, 2025).
AP4S1 also shares sentences with these, for which no sentence is quoted: Ataxia (1 paper); microcephaly (1); neurodevelopmental disorder (1); neurological disease (1); Obesity (1); paraplegia (1); Seizure (1); Spasticity (1).